FUT8 (fucosyltransferase 8)
Diseases named in the same sentence as FUT8 in open-access papers (continued):
Sharing a sentence is not in itself a finding about the gene and the disease.
epilepsy (2 papers, 2023 to 2024). A brain disorder characterized by episodes of abnormally increased neuronal discharge resulting in transient episodes of sensory or motor neurological dysfunction, or psychic dysfunction. "In this study, we focus on the diagnostic and prognostic value of fucosyltransferase 8 (Fut8) on epilepsy and refractory epilepsy." (PMID 37053181, 2023). "By detecting the expression of Fut8 in serum of patients with epilepsy or refractory epilepsy, we clarified the value of Fut8 as a diagnostic and prognostic factor for epilepsy and refractory epilepsy, hoping to provide a basis for the early detection and treatment of refractory epilepsy." (PMID 37053181, 2023). "In conclusion, our experiment confirmed that Fut8 is one of the early diagnoses for predicting refractory epilepsy, but Fut8 was be affected by demographic and clinical features such as the concentration of VPA and seizure of family history." (PMID 37053181, 2023). "A receiver operating characteristic curve showed that the expression of Fut8 could distinguish epilepsy patients from the healthy controls, and the area under curve (AUC)was 0.620." (PMID 37053181, 2023). "However, the expression of Fut8 in the epilepsy group (63.7±23.4 ng/ml) has a increase trend compared with the control group without significant difference." (PMID 37053181, 2023). "Therefore, we will focus on the changes of Fut8 before and after administration in the future experiment to explore the important role of Fut8 in the pathogenesis of epilepsy." (PMID 37053181, 2023). "Previous studies have confirmed that Fut8 is indeed closely related to the occurrence of epilepsy." (PMID 37053181, 2023). "Finally, the difference in the recurrence rate of convulsion in patients with epilepsy or refractory epilepsy within 2 years were observed in different Fut8 expression patients." (PMID 37053181, 2023). "According to survival analysis, the incidence of epileptic seizures in epilepsy patients within 2 years between high and low Fut8 expression were not significantly difference (p = 0.1865)." (PMID 37053181, 2023). "There was a significant difference in the recurrence rate of convulsion within 2 years in the children with refractory epilepsy (p = 0.0493) not epilepsy (p = 0.1865) between the high and low Fut8 expression groups." (PMID 37053181, 2023).
fibrosis (2 papers, 2010 to 2022). the formation of excess fibrous connective tissue in an organ or tissue in a reparative or reactive process. "Our findings are the first to demonstrate that serum FUT8 activity was associated with renal interstitial inflammation and fibrosis in IgAN." (PMID 36039648, 2022).
follicular carcinoma (2 papers, 2010 to 2021). "The number of Fut8-positive cases of follicular carcinomas was relatively low." (PMID 20652009, 2010).
glioblastoma (2 papers, 2018 to 2024). The most malignant astrocytic tumor (WHO grade IV). "FUT8 is highly expressed in patient-derived tumor tissues and glioblastoma cells." (PMID 39728102, 2024).
liver cirrhosis (2 papers, 2016 to 2019). "While the expression level of FUT8 in the normal liver is quite low, it increases in patients with chronic liver diseases, like liver cirrhosis, as well as in HCC patients." (PMID 31451706, 2019). "We have investigated molecular mechanisms underlying by which AFP-L3 is specifically increased in sera of patients with HCC, but not benign liver diseases although expression of FUT8 in the liver is increased in chronic liver diseases such as chronic hepatitis and liver cirrhosis." (PMID 31451706, 2019).
lung squamous cell carcinoma (2 papers, 2020 to 2025). "Poorly differentiated lung squamous cell carcinoma tissue was used as a positive control for FUT8 immunostaining." (PMID 32099910, 2020).
medulloblastoma (2 papers, 2020 to 2021). A malignant, invasive embryonal neoplasm arising from the cerebellum. "High FUT8 expression in medulloblastoma therefore appears to be a positive prognostic indicator, particularly for female patients." (PMID 33323540, 2020).
metastatic melanoma (2 papers, 2020 to 2023). A melanoma that has spread from its primary site to another anatomic site. "An increased core fucosylation mediated by fucosyltransferase 8 is detected in metastatic melanoma, whereas the fucosyltransferase 8 expression could facilitate invasion and tumor dissemination, in part due to a reduced cleavage of the cell adhesion molecule L1." (PMID 32872358, 2020).
metastatic prostate carcinoma (2 papers, 2018 to 2025). A carcinoma that arises from the prostate gland and has spread to other anatomic sites. "Tissue samples that had higher expression of FUT8, except Lane 8, had a significantly lower PSA production and vice versa, which was in accordance with our in vitro western blot analysis suggesting the inhibitory role of FUT8 on the PSA expression in metastatic prostate cancer tissues." (PMID 29339807, 2018).
oral cancer (2 papers, 2021 to 2023). "Studies have shown increasing mRNA levels of FUT8 and core glycoprotein in tumor tissues of oral cancer patients compared with normal oral epithelial/oesophageal tissue." (PMID 36849997, 2023). "In this study, we examined the mRNA expressions of fucosidase (FUCA1) and FUTs (FUTs (FUT3, FUT4, FUT5, FUT6, FUT8) in human oral cancer tissues." (PMID 34703796, 2021). "Collectively, results suggest that elevated mRNA levels of FUT4, FUT5 and FUT8 may be used as worst prognostic indicators for oral carcinoma." (PMID 34703796, 2021). "Therefore, the present investigation was aimed to evaluate the clinical significance of mRNA expressions of various fucosyltransferses (FUT3, FUT4, FUT5, FUT6, FUT8) and fucosidases (FUCA1) in oral cancer progression." (PMID 34703796, 2021).
pancreatic ductal adenocarcinoma (2 papers, 2020 to 2022). An infiltrating adenocarcinoma that arises from the epithelial cells of the pancreas. "For example, in pancreatic ductal adenocarcinoma, FUT8 protein expression was elevated in carcinoma compared with normal pancreatic duct tissues, and FUT8 overexpression was directly correlated with lymph-node metastases and worse relapse-free survival." (PMID 35237113, 2022).
Peritoneal Fibrosis (2 papers, 2021 to 2022). Disorder characterized by a wide range of structural changes in PERITONEUM, resulting from fibrogenic or inflammatory processes. "Since Fut8 is the enzyme responsible for core fucosylation in vivo, we assessed its expression in the peritoneal membrane of rats to determine whether it was associated with peritoneal fibrosis." (PMID 33993842, 2021). "Our previous animal studies found that FUT8 was markedly upregulated, it activated multiple fibrogenic signaling pathways, and its knockdown ameliorated the progression of renal and peritoneal fibrosis." (PMID 36039648, 2022). "Based on our previous in vivo findings, there is increased activation of multiple signaling pathways, such as TGF‐β/Smad and PDGF/ERK, during renal interstitial and peritoneal fibrosis, and inactivation of these pathways by knockdown of FUT8 significantly attenuated fibrotic processes." (PMID 36039648, 2022).
Viral infection (2 papers, 2016 to 2024). "The detailed mechanisms underlying the role of FUT8 in viral infection remain unclear." (PMID 38253527, 2024). "Viral infection-induced FUT8 expression was dependent on EGFR, AKT, and SNAIL, as HCV-infection-induced upregulation of FUT8 mRNA levels and FUT8 promoter activation were attenuated in Huh7 cells after silencing EGFR, AKT, or SNAIL." (PMID 38253527, 2024).
acute myeloid leukemia (1 paper, 2021). Acute myeloid leukemia (AML) is a group of neoplasms arising from precursor cells committed to the myeloid cell-line differentiation. "Indeed, Meis1 aberrant expression actively contributes to acute myeloid leukemia, whereas Fut8 overexpression has been found in non-hematopoietic cancer." (PMID 33733070, 2021).
asthma (1 paper, 2024). "TCR activation is mediated by the Alpha-1,6-fucosyltransferase FUT8, and it is crucial for T cell differentiation into different linages, which shape the pathology of asthma." (PMID 38785919, 2024).
atherosclerosis (1 paper, 2023). A disease characterized by the build-up of fatty material and calcium deposition in the arterial wall resulting in partial or complete occlusion of the arterial lumen. "Our previous studies showed that aberrant fucosylation, especially α-1,6 fucosylation catalyzed by Fut8, is associated with reduced cell migration and the accumulation of cholesterol-enriched foam cells in the early stage of atherosclerosis." (PMID 36670464, 2023). "Importantly, we also found that hypofucosylation of Unc5b regulated by Fut8 enhanced macrophage emigration from intimal lesions and further prevented atherosclerosis through the p-CDC42/p-PAK signaling pathway." (PMID 36670464, 2023). "Moreover, we found that Unc5b was fucosylated by Fut8, which mainly mediated macrophage retention during the progression of atherosclerosis." (PMID 36670464, 2023). "Researchers have found that aberrant glycosylation mediated by Fut8 is often involved in the decreased mobility of foam cells and is responsible for the accumulation of cholesterol-enriched foam cells in the intima in the early stage of atherosclerosis." (PMID 36670464, 2023). "The immunofluorescence colocalization assay results first suggested that fucosyltransferase 8 (Fut8) might participate in the exacerbation of atherosclerosis." (PMID 36670464, 2023). "Then we found that the colocalization of Unc5b, Fut8 and CD68 in the aortic sinus were strongly promoted during the development of atherosclerosis as indicated in the Development group." (PMID 36670464, 2023).
benign meningioma (1 paper, 2024). A grade I, slowly growing meningioma. "However, the gene expression experiments demonstrated that FUT1 and FUT8 were highly expressed in the malignant meningioma—HKBMM—vs the primary benign meningiomas—SUT-MG12 and SUT-MG14." (PMID 38274327, 2024).
bone metastasis (1 paper, 2021). Transfer of a neoplasm from its primary site to bones. "Taken together, our data support that the highly core-fucosylated N-glycan profile of bone metastasis was likely driven by a local increase of RBCs, MKs, platelets, and stromal cells in bone metastases, all of which highly express FUT8, the enzyme conferring core-fucosylation." (PMID 34752419, 2021).
breast tumor (1 paper, 2017). "FUT8 knockdown did not affect the breast tumor growth at primary sites but greatly reduced the lung metastatic ability of 4T1 cells as compared with the control." (PMID 28982386, 2017).
cardiac arrest (1 paper, 2013). Cessation of breathing and/or cardiac function. "Interestingly, ST6GAL1 has been previously associated with Type 2 diabetes, MGAT3 with Crohn's disease, primary biliary cirrhosis and cardiac arrest, and FUT8 with multiple sclerosis, blood glutamate levels and conduct disorder." (PMID 23382691, 2013).
colitis (1 paper, 2022). Inflammation of the colon. "Recently, it has been shown that by inducing trinitrophenol and lipopolysaccharide, the degree of inflammation in FUT8-deficient (FUT8 −/−) mice showed significantly lower inflammation in colitis than in wild-type (FUT8 +/+) mice." (PMID 36499043, 2022).
depression (1 paper, 2025). "In our study, we found that Fut8+/− mice had higher Il6 levels than the Fut8+/+ group, indicating that diminished core fucosylation predisposes mice to depression." (PMID 39864626, 2025). "This is consistent with the findings that our chronic depression model CUS stimulation mice exhibit reduced Fut8 mRNA levels." (PMID 39864626, 2025). "Furthermore, the impact of WP1066 on the expression of inflammatory factors and Fut8 in CUS-induced depression also showed a similar tendency with L-fucose." (PMID 39864626, 2025).
diabetes (1 paper, 2022). "Previous studies found that DDB1-mediated degradation of Cry1 was an important target for insulin action on glucose homeostasis, and the FUT8 was strongly associated with increased susceptibility to diabetes." (PMID 36360309, 2022).
endometrial endometrioid carcinoma (1 paper, 2020). "The gene expression of FUT7 and FUT8 was significantly increased in endometrial endometrioid carcinoma tissues, compared to those of the normal endometrium (P < 0.05)." (PMID 32099910, 2020). "•Fucosyltransferase 8 gene expression is elevated in the tissues affected by endometrial endometrioid carcinoma." (PMID 32099910, 2020). "In conclusion, FUT8 was expressed in endometrial endometrioid carcinoma especially in the glandular part." (PMID 32099910, 2020). "FUT8 gene expression was significantly increased in the tissues of endometrial endometrioid carcinoma compared with those of the normal endometrium, which coincided with the description of Human protein atlas and the previous report." (PMID 32099910, 2020). "•Fucosyltransferase 8 protein is specifically detected in the glands affected by endometrial endometrioid carcinoma." (PMID 32099910, 2020). "Quantitative real-time PCR analysis showed that FUT8 gene expression was significantly elevated in the endometrial endometrioid carcinoma, compared to the normal endometrium." (PMID 32099910, 2020). "In contrast, FUT8 protein was strongly and extensively stained in the gland of the endometrial endometrioid carcinoma." (PMID 32099910, 2020). "•These results suggest that fucosyltransferase 8 might be involved in the proliferation of endometrial endometrioid carcinoma." (PMID 32099910, 2020). "Therefore, significant augmentation of FUT8 gene expression in endometrial endometrioid carcinoma strongly suggests a pivotal involvement in its biology." (PMID 32099910, 2020). "In the present study, we hypothesized that FUT8 was upregulated in endometrial endometrioid carcinoma and regulated its proliferation." (PMID 32099910, 2020). "The immunostaining of FUT8 and Ulex europaeus Agglutinin 1 (UEA-1), a kind of lectin family specifically binding to fucose, was detected endometrial endometrioid carcinoma." (PMID 32099910, 2020). "However, the present study featured a small patient cohort, and we could not identify any association of the levels of FUT8 expression with clinical stages of endometrial endometrioid carcinoma (data not shown)." (PMID 32099910, 2020).
epileptic seizures (1 paper, 2023). "Further, high expression of Fut8 in serums of refractory epilepsy patients was a significant correlated with the incidence of epileptic seizures within 2 years (p<0.05)." (PMID 37053181, 2023).
erythroleukemia (1 paper, 2021). Acute erythroid leukemia characterised by the presence of at least 50% erythroid precursors and at least 20% myeloblasts in the bone marrow. "Besides, FUT8 inhibits erythroid differentiation of MEL cells and K562 cells, which suggests that FUT8 also contributes to erythroleukemia." (PMID 33733070, 2021).
HIV-1 infection (1 paper, 2023). The type species of lentivirus and the etiologic agent of acquired immunodeficiency syndrome (AIDS). "Polymorphisms that alter the function or expression levels of FUT8 could, therefore, impact the antiviral immune response and thus the clinical course of HIV-1 infection." (PMID 37598360, 2023).
lentivirus infection (1 paper, 2021). Virus diseases caused by the Lentivirus genus. "In vitro lentivirus infection was used to construct a stable Fut8-knockout and reintroduced SiHa cell line, gene knockout and reintroduced was verified by LCA blotting." (PMID 34799549, 2021).
meningioma (1 paper, 2024). A generally slow growing tumor attached to the dura mater. "High expression of FUT1, FUT2, FUT3, FUT6, FUT7, and FUT8 in malignant meningioma cell lines—HKBMM and IOMM-Lee—may represent a fucosylation signature of mucin-type O-linked glycosylation in malignant meningiomas." (PMID 38274327, 2024). "FUT1, FUT2, FUT3, FUT6, FUT7, and FUT8 were highly increased in malignant meningioma cell lines." (PMID 38274327, 2024).
neuroblastoma (1 paper, 2023). Neuroblastoma (NB) is the most common solid, extracranial childhood tumor. "hsa-miR-34a has been reported to regulate ALG13, FUT8, GALNT7, and ST3GAL5 in neuroblastoma and hepatocellular carcinoma." (PMID 37188790, 2023).
osteonecrosis (1 paper, 2021). A none disease characterized by death of bone tissue due to a lack of blood supply. "Our previous study has shown that fucosylation is downregulated in glucocorticoid-induced osteonecrosis of the femoral head, suggesting that FUT8-mediated core fucosylation may play a role in osteogenesis." (PMID 34966572, 2021).
ovarian serous carcinoma (1 paper, 2020). "The specific expression of FUT8 in the glandular part is also reported in cases of ovarian serous carcinoma." (PMID 32099910, 2020).
prostate tumour (1 paper, 2025). "In summary, we report FUT8 is upregulated in high grade prostate tumours, and this is linked to a more aggressive tumour phenotype." (PMID 40387385, 2025). "Using an enzyme that specifically cleaves core‐fucosylated N‐glycans, endoglycosidase F3, we show that increased levels of FUT8 in prostate tumours correlates with a core fucosylated N‐glycan structural theme." (PMID 40387385, 2025). "Our findings are consistent with a previous study which revealed FUT8 is a master regulator of cell surface receptors in aggressive prostate tumours and can promote cell survival in androgen depleted conditions." (PMID 40387385, 2025). "Taken together, our findings show in addition to being upregulated in high grade prostate tumour tissue, the levels of FUT8 are also significantly higher in the blood of patients with aggressive disease." (PMID 40387385, 2025). "Here, we monitor FUT8 expression at both the gene and protein level in 8 independent cohorts (comprising > 1500 clinical samples) and confirm upregulation of FUT8 in aggressive high grade prostate tumour tissue." (PMID 40387385, 2025). "Furthermore, we find FUT8‐mediated core fucosylation can be targeted using metabolic fucosylation inhibitors, and that this suppresses the growth of prostate tumours." (PMID 40387385, 2025). "Furthermore, we find that blocking the activity of FUT8 using fucosylation inhibitors can suppress the growth of prostate tumours." (PMID 40387385, 2025).
renal fibrosis (1 paper, 2022). A final common manifestation of a wide variety of chronic kidney diseases characterized by glomerulosclerosis and tubulointerstitial fibrosis. "Our previous research found that blockade of FUT8 had protective effects on the renal tubular cell epithelial‐mesenchymal transition in vitro and renal fibrosis in vivo." (PMID 36039648, 2022). "α‐1,6 Fucosyltransferase (FUT8) appears to play an essential role in the pathogenesis of renal fibrosis." (PMID 36039648, 2022). "FUT8 appears to play an essential role in the pathogenesis of renal fibrosis." (PMID 36039648, 2022). "Therefore, FUT8 appears to play an essential role in the pathogenesis of renal fibrosis." (PMID 36039648, 2022).
tongue cancer (1 paper, 2021). A malignant neoplasm affecting the tongue. "Analyzing the mRNA expression of FUTs and FUCA1 revealed that, mRNA levels of FUTs and FUCA1 were higher with significant up regulation of FUT4 and FUT8 in the tongue carcinoma patients as compared to the buccal carcinoma as a primary site of the disease." (PMID 34703796, 2021). "There was a significant up regulation of FUT3, FUT4, FUT5, and FUT8 (P = 0.019, 0.025, 0.087, and 0.034, respectively) in patients with tongue carcinoma in comparison with patients with buccal carcinoma as a primary site." (PMID 34703796, 2021).